RAB13 (RAB13, member RAS oncogene family)
Diseases named in the same sentence as RAB13 in open-access papers (continued):
Sharing a sentence is not in itself a finding about the gene and the disease.
cancer (16 papers, 2011 to 2025). A tumor composed of atypical neoplastic, often pleomorphic cells that invade other tissues. "The STRING web tool further investigated the underlying molecular mechanism of the RAB13 in the emergence and evolution of cancers." (PMID 37803063, 2023). "As a member of Rab-associated G protein family, RAB13 controls the trafficking and cellular localization of a number of key modulators in cancer and thus affects the tumorigenesis." (PMID 34868230, 2021). "Protrusion-enriched RNAs encode factors linked to cancer progression, such as the RAB13 GTPase and the NET1 guanine nucleotide exchange factor, and are regulated by the tumor-suppressor protein APC." (PMID 33060293, 2020). "This indicates that signaling pathways downstream of constitutively active KRAS are necessary for the effects we observe after knockdown of Rab13 that could be similar in other cancer cells with KRAS mutations." (PMID 32978434, 2020). "Rab13 controls protein trafficking pathways pertaining to cancer growth, including integrin recycling for cell migration and the membrane transport of GLUT4 and VGEFR for glucose uptake and angiogenesis." (PMID 40687836, 2025). "One such Rab GTPases, namely RAB13, controls cellular functions that are often altered in cancer, and found to be up-regulated in different kinds of cancers." (PMID 39192986, 2024). "We used GEPIA 2 to analyze the survival of RAB13 in pan-cancer to look into the relationship between RAB13 expression and prognostic value." (PMID 37803063, 2023). "We conducted a thorough investigation of the status of RAB13 gene changes in human pan-cancer using the cBioPortal database." (PMID 37803063, 2023). "That's why we employed ssGSEA to look at how RAB13 affects immune cell infiltration levels across different cancer types." (PMID 37803063, 2023). "Then, we used UALVAN database to retrieve the data of TCGA cancers to investigate the relationship between RAB13 expression and the pathological stage of various malignancies." (PMID 37803063, 2023). "Although RAB13's function and mechanism in a few cancers are well understood, further research is still needed to determine how RAB13 works in pan-cancer." (PMID 37803063, 2023). "The differential expression of RAB13 between tumor and surrounding normal tissues was investigated across all TCGA cancers using the TIMER2.0 database." (PMID 37803063, 2023). "In this study, we utilized bioinformation analysis technology and numerous databases to thoroughly analyze the function of RAB13 in cancers." (PMID 37803063, 2023). "This study's goal was to investigate RAB13's function in human pan-cancer, and we have also preliminarily explored the relevant mechanisms." (PMID 37803063, 2023). "In this study, we looked at the effects of RAB13 on pan-carcinoma from every angle possible, including its impact on survival, prognosis, genetic and epigenetic alterations." (PMID 37803063, 2023). "Rab13 is recognized as an important driver of cancer progression since the abnormal function of Rab13 is often observed in cancer." (PMID 34632655, 2021). "Based on The Cancer Genome Atlas (TCGA) database, elevated expression of RAB13 has been observed in the majority of cancers and is inversely correlated with patient prognosis." (PMID 34868230, 2021). "Cellular Rab13 has been shown to play a significant role in cancer progression, invasiveness, and metastasis, partly related to the regulation of tight junctions and adherens junction formation." (PMID 32978434, 2020). "RAB13 expression is amplified in the majority of cancers, and its levels correlate with poor prognosis." (PMID 33060293, 2020). "DENND2B, a GEF for Rab13, activates Rab13-mediated exocytosis and enhances the invasiveness of cancer cells." (PMID 27716280, 2016). "Rab13 protein is also shown to be activated during epithelial cell scattering-the process that includes the first steps of carcinoma invasion/metastasis." (PMID 21998723, 2011).
cancer (continued). "Additionally, MYOSLID drives metastasis by regulating epithelial–mesenchymal transition markers such as LAMB3 and Slug while promoting RAB13-mediated cytoskeletal remodeling and enhancing cancer cell invasion." (PMID 40149492, 2025). "In brief, our study preliminarily revealed the role of RAB13 in pan-cancers." (PMID 37803063, 2023). "However, as a member of RAS family, the character of RAB13 in cancer metabolism has been rarely discussed, especially in OC." (PMID 37046345, 2023). "Furthermore, our clinical samples indicated that RAB13 protein expression was markedly elevated in HCC tissues compared to paired non-cancer liver (NCL) tissues." (PMID 36901767, 2023). "RAB13 regulates the proliferation of cancer cells and tumor growth in vivo." (PMID 34141710, 2021). "Therefore, RAB13 is involved in the regulation of several key determinants of cancer cells aggressiveness." (PMID 34141710, 2021). "Moreover, by analyzing published microarray data for NCI-60 cancer cells, RAB13 was further discovered as a target gene relevant to radiosensitivity." (PMID 34868230, 2021). "Furthermore, RAB13 has been reported as a novel biomarker in cancer with its expression correlating negatively with gastric cancer patients’ overall survival (OS) and progression-free survival (PFS)." (PMID 34141710, 2021). "Moreover, Rab13 expression is elevated in some invasive cancers, and Rab13 promotes recycling of integrins and other proteins to the leading edge to enhance migration." (PMID 28106780, 2017). "CRC is a kind of severe cancer with high heterogeneity and genetic factors, so we explored the association between RAB13 expression and somatic mutations in TCGA-COAD by maftools in R. The results showed that somatic mutations differed between RAB13 high and low groups." (PMID 39192986, 2024). "p-value < 0.05) markers previously shown to be regulators of cancer cell stemness (SOX4, RAB13, EZH2)." (PMID 41373578, 2025). "Here, using an inducible system of 3D collective invasion, we find that both RAB13 and NET1 RNAs are localized in invasive cancer spheroids." (PMID 33060293, 2020). "Together, this suggests that β1-integrin+, EGFR+, Rab13+ sEVs are secreted by KRAS-mutant cancer cells, and that these vesicles play important roles in cancer development and progression." (PMID 32978434, 2020). "Examination of in vivo tumors reveals a similar localization of the RAB13 and NET1 RNAs at potential invasive sites, suggesting that this mechanism could provide a targeting opportunity for interfering with collective cancer cell invasion." (PMID 33060293, 2020). "Furthermore, examination of in vivo tumors reveals a similar accumulation of RAB13 and NET1 RNAs at potential invasive sites, suggesting that this mechanism could provide a targeting opportunity for interfering with collective cancer cell invasion." (PMID 33060293, 2020).
tumor (11 papers, 2019 to 2024). "We next evaluated the association between RAB13 expression and tumor immunity using ESTIMATE algorithm." (PMID 39192986, 2024). "Then, we explored the relationships between the expression level of RAB13 and clinical phenotypes with TCGA datasets, which indicated RAB13 was significantly associated with worse prognosis and tumor progression." (PMID 37046345, 2023). "Additionally, RAB13 was negatively connected with mutant-allele tumor heterogeneity in COAD (P < 0.05), CESC (P < 0.05), and HNSC (P < 0.05), while it was favorably correlated with mutant-allele tumor heterogeneity in ACC (P < 0.05), ESCA (P < 0.01), and CHOL (P < 0.05)." (PMID 37803063, 2023). "By scRNA analysis in GEO datasets, we found that RAB13 was observed in tumor cells and macrophages, and cell chat analysis showed that osteoclasts interacted with tumor cells in CRC." (PMID 39192986, 2024). "Our research provides clues to the correlation between RAB13 and appeal genes, providing new therapeutic targets for tumor treatment." (PMID 37803063, 2023). "We did observe, nonetheless, that RAB13 expression in LAML tumor tissues was lower than it was in the nearby tumor tissues." (PMID 37803063, 2023). "Taken together, these results suggest that gallic acid can inhibit autophagy by targeting RAB13 and exert an anti‐tumour activity in LGG." (PMID 34632655, 2021). "But more research on RAB13's tumor-related mechanism is still required." (PMID 37803063, 2023). "We suggest that further explorations of RAB13-related experiments should be warranted to dig its specific functions in tumors, which may bring new strategies and targets for tumor treatment." (PMID 37803063, 2023). "Furthermore, according to the CPTAC, we investigated the RAB13 protein's differential expression in tumor and normal tissues." (PMID 37803063, 2023). "RAB13 was shown to be significantly expressed in tumor tissues, which indicated a poor prognosis." (PMID 37803063, 2023). "Tumor mutational burden (TMB) was shown to be negatively connected with RAB13 in BRCA (P < 0.001), LGG (P < 0.01), PRAD (P < 0.001), PCPG (P < 0.05), and THYM (P < 0.001), but favorably correlated with RAB13 in SKCM (P < 0.01)." (PMID 37803063, 2023). "Moreover, we evaluated the tumor tissues obtained from our hospital and obtained the results that showed that the expression of RAB13 mRNA was negatively correlated with miR-2276-5p." (PMID 34141710, 2021). "We further detected the human RAB13 or NET1 RNAs within the tumor mass." (PMID 33060293, 2020). "The DNA methylation and expression levels of PHYHD1, LTBR, MYBPHL, C22orf42, PRR5, ANKDD1A, RAB13, CAMKV, KIFC3, WNT4 and STAT6 are associated with tumor invasion, and these genes may become the potential genes for targeted therapy." (PMID 31796052, 2019). "Next, the tumor-infiltrating immune cells in CRC was further analyzed by ssGSEA in the two GEO datasets, which showed significantly positive correlations between RAB13 expression and Monocyto-Macropahges or Mast cell." (PMID 39192986, 2024). "We investigated the distribution of the RAB13 and NET1 RNAs in these invasive tumor masses by performing in situ hybridization of tumor tissue sections." (PMID 33060293, 2020). "We also found that putative tumor suppressors, such as FOXP1, STK4, and ATM were frequently hypermethylated and silenced whereas oncogenes, such as UHRF1, MPZL1, CDK14, RACGAP1, and RAB13, were hypomethylated and overexpressed suggesting that DNA methylation changes contribute to PTCL development." (PMID 38464090, 2024). "Moreover, we found that RAB13 silencing enhanced the expression of interferon regulatory factors-1 (IRF1) and IRF4, which are vital factors mediating tumor immunity." (PMID 36901767, 2023).
infection (3 papers, 2024). The state of being infected such as from the introduction of a foreign agent such as serum, vaccine, antigenic substance or organism. "We thus also tested the Rab13 recruitment in the presence of the icsB mutant and found that Rab13 stayed for a shorter time at the BCV compared to the infection of the WT strain (14.3 ± 2.2 min)." (PMID 38316786, 2024).
RAB13 also shares sentences with these, for which no sentence is quoted: B-cell lymphomas (2 papers); lymphoma (2); asthma (1); brain injury (1); head and neck squamous cell carcinoma (1); Insulin resistance (1); nasopharyngeal carcinoma (1); nervous system diseases (1); pan (1); pancreatic (1); pancreatic cancer (1); pancreatic ductal adenocarcinoma (1); rectal cancer (1); stomach neoplasm (1).